FGF23 (fibroblast growth factor 23)
Diseases named in the same sentence as FGF23 in open-access papers (continued):
Sharing a sentence is not in itself a finding about the gene and the disease.
hypophosphatemia (continued). "The present cases of FGF23-related hypophosphatemia, probably induced by alcohol, may provide new insight into the development of continued hypophosphatemia and bone metabolic disturbances among chronic heavy alcohol drinkers." (PMID 34901334, 2021). "Lowered basal levels of 1,25(OH)2D3 in M1‐IKO and M1/M21‐DIKO mice lead, in turn, to reduced intestinal absorption of Ca and P, which causes hypocalcemia and hypophosphatemia that promotes a rise in PTH and a reduction in FGF23 levels, and a broad Cyp27b1 null‐like skeletal phenotype." (PMID 33553989, 2021). "In all these conditions, patients may have hypophosphatemia, elevated FGF23 levels and nephrolithiasis/nephrocalcinosis." (PMID 33815294, 2021). "Raised plasma FGF23 reduces renal phosphate reabsorption by downregulating sodium/phosphate co-transporters NPT2a and NPT2c in the proximal renal tubules, resulting in increased urinary phosphate excretion and hypophosphatemia." (PMID 33660084, 2021). "In RS, hypophosphatemia and hyperphosphaturia, high PTH and 1,25(OH)2D3 levels occasionally reported could be associated with FGF23 elevation." (PMID 34360805, 2021). "Persistent hypophosphatemia however should also raise concern for an FGF23 secreting tumor." (PMID 33191899, 2021). "Hypophosphatemia is a common finding in KTRs, especially in those with immediate graft function and a high pre-transplant serum PTH level due to the significant urinary phosphorus loss driven by the effects of high levels of PTH and FGF-23." (PMID 33919913, 2021). "Mutations in FAMC20 gene have been recently associated with a nonlethal variant of Raine syndrome as a novel form of FGF23-related hypophosphatemia and hyperphosphaturia and proposed to represent a third form of ARHR." (PMID 34068220, 2021). "An additional blood test revealed hypophosphatemia with high intact FGF23 level." (PMID 34901334, 2021). "High FGF23, or a level inappropriately normal for the degree of hypophosphatemia, might indicate a disorder of FGF23 excess." (PMID 33615107, 2021). "Mice with DMP1 deficiency develop rickets and osteomalacia, including growth plate defects, abnormalities in osteocyte differentiation and the osteocytic canaliculi–lacunae system, an increase of FGF23, mild hypercalcemia with normocalciuria, phosphaturia and severe hypophosphatemia." (PMID 34360805, 2021). "XLH is caused by a loss-of-function mutation in thePHEX(phosphate regulating endopeptidase homolog, X-linked) gene, leading to increased circulating levels of fibroblast growth factor 23 (FGF23) and consequent phosphaturia, hypophosphatemia, and low 1,25-dihydroxyvitamin D levels." (PMID 33049132, 2021). "Therefore, the increase in FGF23 produces phosphate wasting and inappropriately low-circulating 1,25(OH)2D3 levels, including secondary hypophosphatemia and hypocalcemia, ectopic calcifications and impaired bone mineralization." (PMID 34360805, 2021). "This explains why other i.v. iron formulations do not cause hypophosphatemia, and why intact (active) FGF23 increases more than c-terminal FGF23 in ferric carboxymaltose-induced hypophosphatemia." (PMID 33815294, 2021). "In mice fed standard chow diet, the modest increase in circulating intact FGF23 observed in Furinosb-/- mice did not cause hypophosphatemia and osteomalacia." (PMID 34149625, 2021). "However, we are aware of genetically confirmed XLH patients with plasma FGF23 levels within the normal range, which should be interpreted as inappropriately normal in the setting of hypophosphatemia." (PMID 33660084, 2021). "It was previously reported that mice carrying an ADHR mutation (R176Q, i.e., loss of P4 Arg in the motif R176HTR179↓SA) in the Fgf23 gene did not develop hypophosphatemia unless they were fed a low-iron diet." (PMID 34149625, 2021).
hypophosphatemia (continued). "As if coinciding with these changes, αKlotho was first reported in 1997, a deficiency of which results in an aging phenotype, and fibroblast growth factor 23 (FGF23), which causes a form of rickets and hypophosphatemia in bone metastasis, was identified in the early 2000s." (PMID 34069053, 2021). "Therefore, the FGF23‐mediated impairment in vitamin D metabolism contributing to hypophosphatemia is an important part of the pathophysiology of renal phosphate‐wasting disorders." (PMID 34950827, 2021). "•Cessation of alcohol led to recovery from FGF23-related hypophosphatemia." (PMID 34901334, 2021). "In addition, increased FGF23 level affects calcitriol synthesis and degradation, thus hindering its ability to counterbalance hypophosphatemia." (PMID 33205007, 2020). "cFGF23 measurements comprise a substantial proportion of physiologically inactive FGF23, so high plasma cFGF23 before iron repletion did not cause hypophosphatemia, nor did its drop after iron treatment affect plasma phosphorus." (PMID 32654663, 2020). "Patients with XLH show local and systemic symptoms, including hypophosphatemia, elevated FGF23 levels, impaired growth, rickets, osteomalacia, bone abnormalities, bone pain, spontaneous dental abscesses, hearing difficulties, enthesopathy, osteoarthritis, and muscular dysfunction." (PMID 32184468, 2020). "Biochemical studies showed hypophosphatemia with undetectable fibroblast growth factor 23 (FGF23)." (PMID 32695531, 2020). "Thus, regaining function in FGF23-Klotho signaling after KTx helps promote urinary phosphate excretion and reduced vitamin D-dependent intestinal absorption of calcium and phosphate, which might explain the association between post-KTx hypophosphatemia and reduced cardiovascular mortality." (PMID 32545510, 2020). "Following successful KTx, patients regain functions of klotho via FGF23-Klotho signaling, and with the previously accumulated FGF23, residual hyperparathyroidism, and the use of calcineurin inhibitors (especially cyclosporine), post-KTx hypophosphatemia can commonly occur up to 86%." (PMID 32545510, 2020). "Hypophosphatemia due to elevated FGF23 is the most obvious contributor, however localised fluctuations in tissue non-specific alkaline phosphatase (TNAP), pyrophosphate, calcitriol and direct effects of FGF23 have been observed to be associated with certain manifestations." (PMID 30808384, 2019). "Hypophosphatemia is the primary mechanism by which elevated serum FGF23 affects bone development." (PMID 30808384, 2019). "Excess FGF23 results in hypophosphatemia, whether induced by direct injection or increased stability of FGF23 (Fgf23-TG), or by downregulation of FGF23-suppressors including PHEX." (PMID 30808384, 2019). "Furthermore, spontaneous dental abscesses have not been reported as clinical features of TIO and iron-induced osteomalacia, which are FGF23-high diseases of hypophosphatemia that develop later in life." (PMID 30808384, 2019). "In addition, the conditional deletion of Fgfr1 in osteocytes partially restored the FGF23 overproduction and rescued the hypophosphatemia and mineralization defect in Hyp mice." (PMID 30972027, 2019). "This may indicate that hereditary hypophosphatemia and/or other effects of FGF23 affects formation of dentin and enamel structures during early dental development." (PMID 30808384, 2019). "Previous insights on FGF23 function have been mostly derived from mouse models, in which both administration of recombinant FGF23 and implantation of FGF23-overexpressing cells result in phosphaturia and hypophosphatemia." (PMID 30736285, 2019). "The Hyp mouse is a murine homolog to the human disease of X-linked dominant hypophosphatemia resembling elevated circulating FGF23 concentrations resulting in renal phosphate wasting, hypophosphatemia, decreased renal 1,25D synthesis, and defects in bone mineralization." (PMID 29977226, 2018).
hypophosphatemia (continued). "A decreased activity of FGF-23 due to SLC34A1 mutation and subsequent hyperphosphaturia and hypophosphatemia, indirectly stimulate synthesis of 1,25(OH)2D that may produce hypercalcemia, hypercalciuria and nephrocalcinosis." (PMID 29904370, 2018). "The main biochemical manifestations of this disorder include hypophosphatemia, inappropriately low or normal tubular resorption of phosphate, low serum calcitriol concentrations, high serum alkaline phosphatase, and high or normal serum FGF-23 concentrations." (PMID 28934935, 2017). "If SFO-induced hypophosphatemia is diagnosed, because elevated FGF23 level and hypophosphatemia are treatable, discontinuation of SFO alone may be sufficient in most cases." (PMID 28953654, 2017). "Even when we fail to identify the localization of tumor in subjects with FGF23-related hypophosphatemic osteomalacia, phosphorus replacement therapy for hypophosphatemia could reduce the bone pain." (PMID 27867811, 2016). "Serum C-terminal FGF23 was found to be above the upper limit of the normal laboratory reference of 123 RU/mL (normal value <120 RU/ml), inappropriately high in the presence of hypophosphatemia." (PMID 27709474, 2016). "The mechanism underlying the development of hypophosphatemia is not known but many arguments suggest a role of FGF23." (PMID 26000018, 2015). "To determine whether egr-1 mediates the hypophosphatemia induced by FGF23 in Hyp mice, we generated the double mutant Hyp/egr-1-/- mice." (PMID 26588476, 2015). "However, if hypophosphatemia is secondary to the increase in FGF23 as demonstrated in other studies, hypophosphatemia duration, several months in some cases, raises questions about the long-term side effects of the drug on bone." (PMID 26000018, 2015). "The renal synthesis of 1,25-(OH)2D from its precursor, 25(OH)D is a rate-limiting step and is tightly regulated by serum-(OH)2D, parathyroid hormone (PTH), FGF23, calcium, and phosphate, with renal 1α-hydroxylase being stimulated by PTH, hypophosphatemia, or hypocalcaemia, and inhibited by FGF23." (PMID 26132292, 2015). "In lab tests the hypophosphatemia, hyperphosphaturia, and elevated FGF23 levels were found." (PMID 24639905, 2014). "MAPK regulation of FGF23 transcription is consistent with the recent findings that activating somatic mutations of RAS causes FGF23-mediated hypophosphatemia in humans and that ERK1/2 activation is involved in FGFR-mediated FGF23 transcription in UMR-106 osteoblasts in vitro." (PMID 25089825, 2014). "Moreover, recent studies have reported that administration of monoclonal FGFR1 activating antibodies stimulates FGF23 production and induces hypophosphatemia." (PMID 25089825, 2014). "The severity of FGF23 level abnormality potentially could contribute to the development of hypophosphatemia to some extent." (PMID 25181387, 2014). "Anti FGF-23 antibodies have been shown to lower FGF-23 levels and improve hypophosphatemia in animal studies and may be an area of further research to improve bone mineralization after transplant." (PMID 24605319, 2014). "Additionally, the Fam20c cKO mice developed hypophosphatemia with a remarkable elevation of the serum FGF23 level." (PMID 22615579, 2012). "So we can propose that higher values of FGF23 with its phosphaturic action and the resultant hypophosphatemia may share, among other factors, in the process of diminished BMD in these particular patients." (PMID 22551310, 2012). "Moreover, the regulation of the major known phosphate regulating hormones, PTH, 1,25 Dihydroxycholecalciferol, FGF23 in response to hypophosphatemia was intact and suggests rather compensatory adaptation." (PMID 22859939, 2012). "However, recent research also points to persistent posttransplant elevations of fibroblast growth factor-23 (FGF-23) as playing a major role in posttransplant hypophosphatemia and suppression of 1α-hydroxylase activity in the kidney." (PMID 22811905, 2012).
hypophosphatemia (continued). "Based on observations that Dmp1 null mice show osteomalacia accompanied by hypophosphatemia and elevated FGF-23 levels, this study set out to further characterize the skeletal abnormalities in Dmp1 null mice and determine the mechanisms responsible for those defects." (PMID 21542006, 2011). "In addition, the abnormal fibroblast growth factor 23 (FGF-23) expression in osteocytes, elevated circulating FGF-23 levels, and hypophosphatemia were rescued." (PMID 20734454, 2011). "In such subjects, FGF-23 concentrations have been noted to be elevated, and it is possible that elevations in the concentrations of this growth factor are responsible for the hypophosphatemia seen in this situation." (PMID 18288501, 2008). "While hypophosphatemia has known adverse effects, including muscle cramping, weakness, respiratory depression, rhabdomyolysis, and osteomalacia, the clinical implications of low FGF-23 remain unclear." (PMID 40663633, 2026). "Thus, it is important to note that it is plausible to harbor rare variants of PHEX, which are not yet recognized to be pathogenic for FGF23-mediated hypophosphatemia." (PMID 41445556, 2025). "It is possible to carry rare variants of PHEX that have not yet been identified as pathogenic for FGF23-mediated hypophosphatemia, and the current genetic tests harbor limitations and may not detect all possible pathogenic genetic causes." (PMID 41445556, 2025). "Furthermore, it has been shown that iron deficiency itself leads to upregulation of FGF23 transcription and cleavage, although these changes occur in parallel such that the state of iron deficiency itself does not lead to hypophosphatemia." (PMID 41445551, 2025). "Furthermore, the study also demonstrated that highly sensitive IHC with PIDs could aid in the differential diagnosis of FGF23-related hypophosphatemia of unknown origin." (PMID 39963340, 2025). "It is also important to check 25OHD levels, as normal values (as seen here) help differentiate TIO from nutritional vitamin D deficiency, where low 25OHD would lead to secondary hypophosphatemia with appropriately low 1,25 Vit D but without the FGF-23-driven renal wasting profile." (PMID 40951211, 2025). "Thus, some carbohydrate moieties that are incorporated into drugs to enable the gradual release of iron molecules are suspected to interfere with the posttranslational modification of FGF23 in patients with intravenous iron preparation-induced FGF23-related hypophosphatemia." (PMID 39963340, 2025). "Moreover, pharmacological activation of FGFR1 by monoclonal antibodies in adult mice led to increased serum FGF23 levels and mild hypophosphatemia, and the same monoclonal antibody in cultured rat calvarial osteoblasts induced Fgf23 mRNA expression and protein secretion into the culture medium." (PMID 41473314, 2025). "It is important to recognize FGF23-mediated persistent hypophosphatemia and its associated osteomalacia, irrespective of PHEX gene status, as it may be effectively managed with burosumab regardless of its underlying etiology." (PMID 41445556, 2025). "The biochemical hallmark of TIO includes renal phosphate wasting-induced hypophosphatemia, elevated levels of parathyroid hormone (PTH) and alkaline phosphatase (ALP), inappropriately normal or frankly low 1, 25-dihydroxyvitamin D, and inappropriately normal or elevated FGF23 levels." (PMID 38887276, 2024). "In addition, FGF23 reduces the production of 1,25(OH)2D, which can increase intestinal Pi absorption by upregulating the expression of the type IIb Na+/Pi cotransporter NaPi-IIb, leading to hypophosphatemia." (PMID 39415983, 2024). "Interestingly, solid tumors like neuroendocrine tumors including small cell lung cancer of the lung or prostate and also hematologic malignancies are able to produce FGF23 and could lead to FGF23-related hypophosphatemia." (PMID 35665817, 2023). "However, hypophosphatemia with increased renal excretion may be FGF23‐mediated or non‐FGF23‐mediated." (PMID 36511653, 2023).
hypophosphatemia (continued). "In conclusion, increased cFGF23 concentrations, especially in the setting of hypophosphatemia, can be wrongly classified as a FGF23‐associated disorder, while iFGF23 concentrations may be normal, for example in the setting of iron deficiency." (PMID 37808399, 2023). "In conclusion, this study adds convincing support to the hypothesis that mosaic expression of hyperactive HRAS in bone, and not skin, leads to increased bioactive FGF23 secretion and, consequently, the FGF23-mediated hypophosphatemia and osteomalacia observed in CSHS." (PMID 36943390, 2023). "In the clinical exploration of a hypophosphatemia in patients presenting high phosphaturia, PTH, and FGF23 are useful to differentiate causes linked to hyperparathyroidism and other diseases linked with PTH increase from FGF23-mediated forms (XLH, ADHR, ARHR1)." (PMID 35665817, 2023). "This may be of great interest for future studies, since FGF23 levels are expected to drastically change after intravenous iron substitution therapy, along with the resulting changes in serum phosphate levels and transient hypophosphatemia." (PMID 37375595, 2023). "The four initially classified non-FGF23 related hypophosphatemia patients with an increased FGF23 concentration (leading to the 82% specificity) included 2 patients who in retrospect might have had FGF23-related hypophosphatemia due to ectopic overproduction of FGF23 by a neuroendocrine tumor." (PMID 35665817, 2023). "Tumor-induced osteomalacia (TIO) is an uncommon paraneoplastic syndrome characterized by overproduction of FGF-23 by the tumor as well as inappropriately normal or low levels of vitamin D due to impaired hydroxylation leading to phosphate wasting by the kidney and eventual hypophosphatemia." (PMID 37342302, 2023). "Moreover, excess circulating FGF23 can lead to hypophosphatemia and tumor-induced osteomalacia." (PMID 35159314, 2022). "A discrepancy between phosphate dependent- and independent effects has been demonstrated in Hyp mouse studies: In the murine model system, deficient mineralization could be corrected by inactivation of osteopontin (OPN) independently of correcting hypophosphatemia or FGF23 levels." (PMID 35399930, 2022). "Thus, a dual hit hypothesis with local, PHEX/FGF23/OPN induced affection of mineralized tissues combined with systemic, FGF23-induced hypophosphatemia could be hypothesized." (PMID 35399930, 2022). "In diseases of FGF23 over production where renal function is maintained, such as X‐linked hypophosphatemia (XLH) and autosomal dominant hypophosphatemic rickets (ADHR), high levels of FGF23 reduce 1,25D production and cause hypophosphatemia, impaired growth, rickets, and osteomalacia." (PMID 35656701, 2022). "Furthermore, rare diseases with FGF23 excess such as X-linked hypophospatemic rickets (XLH), an X-linked dominant disease with FGF23 overexpression and consecutive hypophosphatemia, do not necessarily present with LV hypertrophy." (PMID 35160052, 2022). "However, mice with high serum levels of FGF23, hypophosphatemia, bone and dentin defects due to FAM20C deficiency are not rescued with DMP1 over-expression." (PMID 34360805, 2021). "An important opportunity to differentiate TIO from other phosphate wasting diseases in register data is that functional and anatomical imaging will be required to locate the FGF23-secreting tumor while this will not be the case for competing causes of hypophosphatemia." (PMID 33818653, 2021). "Additionally, the association between the development of hypophosphatemia and serum FGF23 levels was not discussed in that report." (PMID 34901334, 2021). "Therefore, the effect of hypercortisolism on FGF23 and urinary phosphate excretion should be further evaluated in a prospective setting and all patients with CS should be evaluated for hypophosphatemia, especially when it concerns CS from ectopic ACTH production." (PMID 34659120, 2021).